TRPM4 (transient receptor potential cation channel subfamily M member 4)
Diseases named in the same sentence as TRPM4 in open-access papers (continued):
Sharing a sentence is not in itself a finding about the gene and the disease.
TRPM4 also shares sentences with these, for which no sentence is quoted: cardiac arrhythmias (9 papers); cardiomyopathy (4); psychosis (3); temporal lobe epilepsy (3); colorectal tumor (2); dermatitis (2); hypertrophy (2); infarction (2); intracerebral hemorrhage (2); kidney cancer (2); myocardial ischemia (2); Obesity (2); Parkinson disease (2); prostatic intraepithelial neoplasia (2); subarachnoid hemorrhage (2); type 2 diabetes (2); Ventricular arrhythmia (2); acute liver failure (1); Alzheimer disease (1); amyotrophic lateral sclerosis (1); angioedema (1); atrial septal defect (1); atrioventricular septal defect (1); autosomal dominant polycystic kidney disease (1); B-cell non-Hodgkin lymphoma (1); brain diseases (1); Brugada syndrome 1 (1); Cerebral atrophy (1); cerebral infarcts (1); CHARGE syndrome (1).
A further 43 diseases each share a sentence with TRPM4 in 1 paper.